STAG1 (STAG1 cohesin complex component)
Description:
Component of cohesin complex, a complex required for the cohesion of sister chromatids after DNA replication. The cohesin complex apparently forms a large proteinaceous ring within which sister chromatids can be trapped. At anaphase, the complex is cleaved and dissociates from chromatin, allowing sister chromatids to segregate. The cohesin complex may also play a role in spindle pole assembly during mitosis.
Synonyms: SA1; SA-1; SCC3A; MRD47
Tractability: Small molecule: a structure with a bound ligand is known. PROTAC: UniProt records ubiquitination sites on it; ubiquitination databases record sites on it; its protein half-life has been measured.
Gene: Protein-coding gene on chromosome 3 (136,336,234 to 136,752,432, reverse strand). Ensembl gene ENSG00000118007.
Subcellular location: Nucleus; Chromosome; Chromosome, centromere
Subcellular location (Human Protein Atlas): Nucleoplasm; Nuclear bodies; Primary cilium
Pathways (Reactome):
Cell Cycle: Cohesin Loading onto Chromatin; Establishment of Sister Chromatid Cohesion; Resolution of Sister Chromatid Cohesion; Separation of Sister Chromatids
Metabolism of proteins: SUMOylation of DNA damage response and repair proteins
Reproduction: Meiotic synapsis
Signal Transduction: Estrogen-dependent gene expression
Gene Ontology:
Molecular function: protein binding; chromatin binding
Biological process: mitotic spindle assembly; establishment of mitotic sister chromatid cohesion
Cellular component: chromatin; cohesin complex; mitotic spindle pole; nuclear body; nuclear matrix; nucleoplasm; chromosome; chromosome, centromeric region; cytosol; nucleus
Genetic constraint (gnomAD): Loss-of-function variants: 7 observed, 82.45 expected, observed/expected ratio (o/e) 0.0849, 90% interval 0.047 to 0.16. The upper end of that interval is the gene's LOEUF score, 0.16, which puts it in group 1 of 6, group 1 being the genes least tolerant of losing a copy. Missense variants: 664 observed, 1,030.7 expected, observed/expected ratio (o/e) 0.64, 90% interval 0.6 to 0.69. Synonymous variants: 351 observed, 355.26 expected, observed/expected ratio (o/e) 0.99, 90% interval 0.9 to 1.08.
Gene-disease validity (ClinGen):
ClinGen rates the evidence that STAG1 causes each of these diseases.
complex neurodevelopmental disorder (autosomal dominant): Definitive. A disorder that involves more than one phenotype associated with the central nervous system, including but not limited to intellectual disability, autism, and seizures (epilepsy).
Homologues: Orthologues: macaque STAG1 (100% identical), chimpanzee STAG1 (99% identical), pig STAG1 (99% identical), rabbit STAG1 (99% identical), mouse Stag1 (99% identical), rat Stag1 (99% identical), dog STAG1 (99% identical), guinea pig STAG1 (97% identical), tropical clawed frog stag1 (90% identical), zebrafish stag1a (86% identical), zebrafish stag1b (85% identical), Caenorhabditis elegans scc-3 (30% identical), and 1 more. Paralogues in human: STAG2 (71% identical), STAG3 (48% identical).
Diseases named in the same sentence as STAG1 in open-access papers:
STAG1 is named in the same sentence as 74 diseases in open-access papers, as found by Europe PMC text mining. Sharing a sentence is not in itself a finding about the gene and the disease. The quoted sentences say what the papers report.
Cornelia de Lange syndrome (7 papers, 2014 to 2025). A rare syndrome characterized by low birth weight, delayed growth, intellectual disabillity, behavioral problems, and a distinctive facial appearance (thin, arched eyebrows, low set ears, small teeth, and small nose). "Cohesinopathy in humans leads to diseases with cancer proneness, developmental malformation, and/or intellectual disability and behavioral issues, such as Cornelia de Lange syndrome or mutations in STAG1 or STAG2." (PMID 29943428, 2018). "Based on mouse studies, it has also been suggested that Stag1 mutation can cause Cornelia de Lange syndrome." (PMID 24992337, 2014). "The gene STAG1, which has been annotated to the cola-associated CpG site cg14591243, has been found to be associated with sister chromatid cohesion during cell division and diseases, including intellectual developmental disorder and Cornelia de Lange syndrome." (PMID 38018434, 2023). "It has been reported that the STAG1-related clinical manifestations overlapped with the phenotype of Cornelia de Lange syndrome." (PMID 41210242, 2025). "Although STAG1-associated disorders are part of the cohesinopathies, they do not share several features of Cornelia de Lange syndrome." (PMID 39336775, 2024). "Variants in genes encoding various structural or functional components of the cohesin complex, including RAD21, SMC1A, SMC3, BRD4, STAG1/2, NIPBL, HDAC8, WAPL, ANKRD11 and in single individuals PDS5A and ESPL1, have been implicated in Cornelia de Lange Syndrome (CdLS)." (PMID 32193685, 2020).
bladder cancer (6 papers, 2017 to 2024). "We transplanted STAG2 mutated (p.K983*) UM-UC-3 bladder cancer cells, which were transduced with in vitro validated shRNAs targeting STAG1, into immunocompromised mice to evaluate the effects of partial STAG1 suppression in vivo." (PMID 32467316, 2020). "Restoration of STAG2 expression in a mutated bladder cancer model alleviates the dependency on STAG1." (PMID 28691904, 2017). "This suggests that, compared with STAG2+ cells, STAG2− cells are more dependent on STAG1 on a large, context-independent scale, a finding consistent with previous knockdown of STAG1 in bladder cancer and Ewing’s cell line panels." (PMID 34462321, 2021). "We observed that STAG2-mutant cells were strongly dependent on STAG1, as has been recently reported in the context of bladder cancer and Ewing sarcoma cell lines." (PMID 33351783, 2021). "Consistent with the results obtained in bladder cancer cells, STAG2 mutation status was also linked to STAG1 dependency in a panel of four Ewing sarcoma cell lines." (PMID 28691904, 2017). "siRNA experiments revealed that STAG2 status represented a predictive marker for the sensitivity to STAG1 depletion across the bladder cancer cell line panel." (PMID 28691904, 2017). "All cohesin components, except STAG1, have tumour suppressor roles in several cancer types, including leukaemia, sarcoma, glioblastoma and bladder cancer." (PMID 28430577, 2017). "STAG1 inactivation inhibits the proliferation of STAG2 mutated but not wild-type bladder cancer and Ewing sarcoma cell lines." (PMID 28691904, 2017). "We show that the synthetic lethal interaction between STAG1 and STAG2 is observed in isogenic HCT 116 and KBM-7 cells as well as in bladder cancer and Ewing sarcoma cell lines." (PMID 28691904, 2017). "Using a similar approach, we generated stable STAG1 KO in sarcoma (U2OS), uterine carcinoma (MFE-319) and bladder carcinoma (RT-112) cell lines that have both genes WT, but with a different number of copies." (PMID 28430577, 2017). "In mutant bladder cancer models, restoring STAG2 expression mitigated dependence on STAG1." (PMID 39390002, 2024). "STAG1 inactivation inhibits the proliferation of STAG2 mutations but not in Ewing’s sarcoma and bladder cancer." (PMID 39390002, 2024). "However STAG2, but not STAG1, has been identified as a tumour suppressor in leukaemia, sarcoma, glioblastoma and bladder cancer." (PMID 28430577, 2017). "STAG1 depletion prevented colony formation and abolished sister chromatid cohesion selectively in STAG2 mutated UM-UC-3 (F983fs) but not in STAG2 wild-type UM-UC-5 bladder cancer cells." (PMID 28691904, 2017).
Ewing sarcoma (6 papers, 2017 to 2024). A small round cell tumor that lacks morphologic, immunohistochemical, and electron microscopic evidence of neuroectodermal differentiation. "In additional, several other non-DNA binding transcriptional regulators are present among all Supertargets: a component of the cohesion complex STAG1 (Ewing sarcoma), SMARCA2 (lung) and SMARCAL1 (osteosarcoma)." (PMID 37297004, 2023). "In Ewing sarcoma A673 cells, non-CTCF cohesin sites were detected with an antibody against SMC1, but they showed little enrichment for RAD21, STAG1 or STAG2." (PMID 36424654, 2022).
developmental delay (4 papers, 2021 to 2025). "STAG1 cohesinopathies commonly describe ID, growth defects, and craniofacial abnormalities, as well as developmental delay and behavioural abnormalities." (PMID 40361893, 2025).
glioblastoma (4 papers, 2014 to 2026). The most malignant astrocytic tumor (WHO grade IV). "For example, STAG1-deficient mouse embryo fibroblasts show increased aneuploidy, and functional assays in glioblastoma cell lines have linked loss of STAG2 expression to chromatid cohesion defects and aneuploidy." (PMID 24270882, 2014).
Intellectual disability (4 papers, 2021 to 2025). "The two patients showed a different degree of intellectual disability, motor and speech delay and behavioral abnormalities, suggesting the clinical variability of the STAG1-associated phenotype." (PMID 39336775, 2024). "Reports of STAG1-related cohesinopathies, including ours, have consistently described developmental and intellectual disabilities." (PMID 40361893, 2025). "Therefore, the crucial aspect of the STAG1-related phenotype is represented by the intellectual disability/neurodevelopmental delay that is found in all the cases described so far." (PMID 39336775, 2024).
leukemia (4 papers, 2017 to 2021). A malignant (clonal) hematologic disorder, involving hematopoietic stem cells and characterized by the presence of primitive or atypical myeloid or lymphoid cells in the bone marrow and the blood. "In the background of STAG2 absence, additional STAG1 loss abrogated hematopoiesis, consistent with the reported synthetic lethality between STAG1 and STAG2 in leukemia cell lines and the redundancy in STAG1 and STAG2 function in chromatid segregation." (PMID 33799787, 2021). "Collectively, these experiments identify STAG1 as a vulnerability of STAG2 mutated cells in engineered solid cancer and leukemia models." (PMID 28691904, 2017).
glioma (3 papers, 2013 to 2022). A benign or malignant brain and spinal cord tumor that arises from glial cells (astrocytes, oligodendrocytes, ependymal cells).
hepatocellular carcinoma (3 papers, 2022 to 2025). A malignant tumor that arises from hepatocytes. "Stromal antigen 1 (STAG1), a component of cohesion, is overexpressed in various cancers, but it is unclear whether it has a role in the transcriptional regulation of hepatocellular carcinoma (HCC)." (PMID 36052535, 2022).
acute myeloid leukemia (2 papers, 2021 to 2022). Acute myeloid leukemia (AML) is a group of neoplasms arising from precursor cells committed to the myeloid cell-line differentiation. "We developed models of cohesin-mutant myelodysplastic syndromes and acute myeloid leukemia and demonstrated a shift from STAG2- to STAG1-cohesin complexes, increased DNA damage, and sensitivity to PARP inhibition." (PMID 33351783, 2021). "For example, somatic mutations in the eight genes that comprise the cohesin ring (SMC1A, SMC3, STAG1, STAG2, RAD21) and the cohesin-ring support genes (NIPBL, MAU2, WAPL, PDS5A, PDS5B) and CTCF are frequently found in many cancer types and are especially common in acute myeloid leukemia (AML)." (PMID 36171609, 2022).
Alzheimer disease (2 papers, 2021 to 2023). A progressive, neurodegenerative disease characterized by loss of function and death of nerve cells in several areas of the brain leading to loss of cognitive function such as memory and language. "The comparison of our anxiety-related genes with human GWAS for neurological conditions identified Stag1 and Sorcs3 associated with four conditions including “Alzheimer's disease”, “autism spectrum disorder, “depression”, “feeling nervous”, “feeling worry”, and “neuroticism”." (PMID 33431988, 2021).
atherosclerosis (2 papers, 2024 to 2025). A disease characterized by the build-up of fatty material and calcium deposition in the arterial wall resulting in partial or complete occlusion of the arterial lumen. "Six shared loci that were shared across all traits in the analysis, all with known associations with atherosclerosis (nearest genes: MAT2A, IRS1, STAG1, PVRL2, OPRL1, ARVCF)." (PMID 40313769, 2025).
epilepsy (2 papers, 2019 to 2025). A brain disorder characterized by episodes of abnormally increased neuronal discharge resulting in transient episodes of sensory or motor neurological dysfunction, or psychic dysfunction. "One patient had a microdeletion, classified here as possibly pathogenic, which includes STAG1, now linked with epilepsy as a cohesinopathy, and one patient carried a de novo intragenic duplication in FGF12 in which SNVs have recently been reported in patients with epileptic encephalopathies." (PMID 30866059, 2019).
Obesity (2 papers, 2024). Accumulation of substantial excess body fat. "A total of 12 significant SNPs associated with BMI were identified, of which 7 SNPs were also significantly associated with obesity, including rs1337406 (WLS), rs673612 (NTNG1), rs4449107 (FAM84A), rs9820485 (STAG1), rs73247924 (CCKAR), rs2083069 (ACADSB), and rs4942190 (DNAJC15)." (PMID 38807991, 2024).
ovarian carcinoma (2 papers, 2017 to 2021). A malignant neoplasm originating from the surface ovarian epithelium. "We predict that STAG3 plays a role in ovarian cancer tumorigenesis, based on its gene fusions and upregulated expression, as well as the central role in cancer of the mitotic cohesin proteins STAG1 and STAG2, whose mutation or inactivation cause aneuploidy." (PMID 34215221, 2021). "Using STAG1 to query the ovarian cancer network, we associated the gene to known function in cell cycle." (PMID 27836980, 2017).
schizophrenia (2 papers, 2022 to 2025). A major psychotic disorder characterized by abnormalities in the perception or expression of reality. "We report association at exome-wide significance between rare PTVs and damaging missense variants in STAG1 and schizophrenia." (PMID 40753099, 2025). "Given the suggestive evidence implicating this gene by two independent study designs, STAG1 was considered by both studies to be a highly likely schizophrenia causal gene." (PMID 40753099, 2025). "In STAG1, both PTVs and missense variants are associated with schizophrenia and DD." (PMID 40753099, 2025). "We identify associations for STAG1 and ZNF136 at exome-wide significance, genes that were previously implicated in schizophrenia by the SCHEMA study at a false discovery rate of 5%." (PMID 40753099, 2025). "Both STAG1 and ZNF136 were previously implicated in schizophrenia by the SCHEMA study at FDR < 5%12, with further support for these associations now provided in the new case-control sample." (PMID 40753099, 2025). "By implicating STAG1 at exome-wide significance in schizophrenia, we contribute further evidence suggesting an aetiological role for disrupted chromatin organisation in this disorder." (PMID 40753099, 2025). "Moreover, STAG1 and KLC1 have fine-mapped common variant signals in schizophrenia." (PMID 40753099, 2025). "In conclusion, our study implicates STAG1 and ZNF136 in schizophrenia with exome-wide significance and 6 additional genes at FDR < 5%." (PMID 40753099, 2025).
Anxiety (1 paper, 2021). Intense feelings of nervousness, tension, or panic often arise in response to interpersonal stresses. "The roles of Stag1 and Sorcs3 in anxiety were not reported before, but the human GWAS data and our mice GWAS data imply that there could be a connection between these genes and anxiety." (PMID 33431988, 2021).
autism spectrum disorder (1 paper, 2021). A spectrum of developmental disorders that includes autism, and Asperger syndrome. "STAG1 was associated with autism spectrum disorder, feeling nervous, feeling worry and neuroticism, whereas SORCS3 was associated with Alzheimer, depression, feeling nervous and neuroticism." (PMID 33431988, 2021).
breast carcinoma (1 paper, 2013). "For instance, STAG1 is a cell cycle regulator and its overexpression is reported for breast cancer and cellular proliferation, while the methylation of RB1 by SMYD2 enhances cell cycle progression." (PMID 23922792, 2013).
Failure to thrive (1 paper, 2025). Failure to thrive (FTT) refers to a child whose physical growth is substantially below the norm. "Features such as short stature, failure to thrive, scoliosis, vertebral anomalies, and rib fusion have been documented, particularly in individuals with STAG2 variants, but are also observed in STAG1-related cases." (PMID 40361893, 2025).
heart defects (1 paper, 2025). "Strikingly, the pregnancies of 66.7% cases (4/6) with SVs of STAG1 were abnormal (such as IUGR, increased nuchal translucency, hydramnios, heart defects)." (PMID 41210242, 2025).
holoprosencephaly (1 paper, 2022). Holoprosencephaly (HPE) is a complex brain malformation resulting from incomplete cleavage of the prosencephalon, occurring between the 18th and 28th day of gestation, and affecting both the forebrain and face, which results in neurological manifestations and facial anomalies of variable severity. "Mouse studies have shown that Stag1 and Scm1a are expressed in prosencephalic neural folds, consistent with forebrain morphogenesis and holoprosencephaly pathogenesis." (PMID 35887945, 2022).
liver fibrosis (1 paper, 2023). "In summary, the STAG1–HIF1α signalling pathway may contribute to the angiogenic role of circRNA‐007371 in liver fibrosis." (PMID 36854930, 2023).
melanoma (1 paper, 2022). A malignant, usually aggressive tumor composed of atypical, neoplastic melanocytes. "However, our in-depth analysis on the TAD boundaries reveal that the switch of STAG2 to STAG1 at the TAD boundaries could be actually associated with the expansion of TADs upon STAG2 knockdown in melanoma cells." (PMID 35388001, 2022). "Here we show that depletion of STAG2 in melanoma cells leads to expansion of topologically associating domains (TADs) and enhances the formation of acetylated histone H3 lysine 27 (H3K27ac)-associated DNA loops at sites where binding of STAG2 is switched to its paralog STAG1." (PMID 35388001, 2022). "To characterize the role of STAG2 in 3D genome organization in melanoma cells, we carried out ChIP-seq against STAG2, STAG1, SMC1A, and CTCF as well as Hi-C analyses in M14 melanoma cells stably expressing inducible shRNA of STAG26." (PMID 35388001, 2022).
mental retardation autosomal dominant 47 (1 paper, 2025). "The heterozygous STAG1 gene (OMIM*604358) variants are associated with autosomal dominant intellectual developmental disorder 47, known as mental retardation autosomal dominant 47 (MRD47, OMIM#617635)." (PMID 41210242, 2025). "Autosomal dominant intellectual developmental disorder 47, alias mental retardation autosomal dominant 47 (MRD47, OMIM #617635) is caused by heterozygous variants in the STAG1 gene (OMIM*604358) on chromosome 3q22.3." (PMID 41210242, 2025).
multiple myeloma (1 paper, 2023). "In the case of multiple myeloma, all protein-coding genes except for two (ZWILCH and STAG1) are underexpressed." (PMID 37963971, 2023).
myeloid malignancies (1 paper, 2021). "Patients with cohesin-mutant myeloid malignancies never present with complete, biallelic inactivation of any cohesin subunit, with the notable exception of STAG2, which has a paralog, STAG1." (PMID 33351783, 2021).
myeloma (1 paper, 2023). "In this regard, the finding that every gene in the cell division-associated communities for MM (with the exception of ZWILCH and STAG1) is underexpressed, could mislead to the conclusion that the myeloma cells are not proliferating." (PMID 37963971, 2023).
Roberts syndrome (1 paper, 2025). "Other cohesinopathies, such as CdLS and Roberts syndrome, have been associated with skeletal defects, raising the possibility that STAG1 dysfunction may similarly impact bone integrity." (PMID 40361893, 2025).